BRCA2 (BRCA2 DNA repair associated)
Diseases named in the same sentence as BRCA2 in open-access papers (continued):
Sharing a sentence is not in itself a finding about the gene and the disease.
cancer (continued). "BRCA1 or BRCA2 germline mutations predispose to breast, ovarian and other cancers." (PMID 34389725, 2021). "Furthermore, replication stress-induced RAD51 recruitment remains intact in BRCA2-deficient cancer cells and BRCA2-hypomorphic mutant embryonic stem cells." (PMID 32938550, 2021). "Furthermore, mice administered the WRNi displayed elevated DNA damage and marked inhibition of BRCA2-deficient tumor growth in the xenograft model, in agreement with the hypersensitivity of BRCA2-deficient cancer cells to the WRNi." (PMID 34772932, 2021). "For example, inherited mutations in the fundamental genes involved in DNA repair or recombination, such as BRCA2, might be expected to result in predispositions to cancers of all types, but they only increase cancer risk in a limited subset of tissues." (PMID 33491650, 2021). "We anticipated that treatment with sublethal doses of WRNi could potentiate olaparib cytotoxicity in BRCA2-mutated cancer cells." (PMID 34772932, 2021). "Therefore, increasing fork instability burden through targeted inhibition of compensatory fork stabilizing factors is a promising therapeutic approach to target human cancers with BRCA2 loss-of-function mutations." (PMID 34772932, 2021). "Therefore, to test the effect of CAM833 on RAD51 clustering, we used SMLM on patient-derived EUFA423 cells bearing compound heterozygosity for the cancer-associated BRCA2 truncating alleles 7691insAT and 9000insA." (PMID 33662256, 2021). "L82 was also selectively toxic in BRCA2 deficient or ATM deficient cancer cells and 3D-spheroids." (PMID 34373746, 2021). "We proposed that overexpression of BRCA2 may counteract the sensitization of BRCA-deficient cancer cells to CPT-11-induced DNA damage after curcumin treatment." (PMID 33922657, 2021). "Importantly, these OB-folds are also critical for the DNA repair activity of BRCA2 and are the location of numerous cancer associated mutations." (PMID 34283091, 2021). "Thus, the in vivo data are consistent with results from cell-based assays demonstrating preferential killing of BRCA2-deficient cancer cells by WRN helicase inhibition." (PMID 34772932, 2021). "RAD52 inactivation increased cell death in lung tumors and in BRCA2-deficient cancer cells." (PMID 34201502, 2021). "POLQ overexpression has also been observed in cancers with BRCA1/BRCA2 mutation, suggesting that it may represent an adaptive response to elevated replication-associated DSB burden, although the precise mechanism of upregulation remains to be elucidated." (PMID 33385162, 2020). "The CRC risk for men carrying the BRCA2 mutation is unknown, but such men likely warrant increased cancer surveillance." (PMID 33260537, 2020). "Therefore, the unique molecular traits of each BRCA protein create a difference between BRCA1- and BRCA2-mutated cancers." (PMID 32269964, 2020). "BRCA1 and/or BRCA2 mutations are frequently detected in both cancer types." (PMID 32250967, 2020). "However, BRCA1 or BRCA2-null cancer cells are deficient in HR and the problems caused by PARP inhibition become lethal even in the absence of exogenous genotoxic stress." (PMID 32029902, 2020). "Multiple studies have indicated that BRCA2 dysfunction causes various cancers." (PMID 31987042, 2020). "Moreover, given the apparent predominant development of synchronous but distinct cancers in BRCA2 mutation carriers, the contribution of genomic instability at a single cell level also needs to be investigated." (PMID 32022473, 2020). "The main conclusion from our model is that DSS1-RAD52 interaction could allow rescue for BRCA2-deficiency in cancer cells by promoting RAD52-mediated activities via SSA and BIR pathways." (PMID 31799622, 2020). "The goal of achieving the highest degree of cancer risk reduction is the primary driver for women with BRCA1 or BRCA2 mutations in selecting an intervention and a sequence of interventions, regardless of whether it is non-surgical or surgical." (PMID 33014209, 2020).
cancer (continued). "In contrast, BRCA2 mutation cancers are mainly luminal type and are ER positive." (PMID 33299637, 2020). "Also the BRCA2-9326insA founder variant, usually present in Germany and Hungary, was detected in Sicilian individuals (7 PV carriers, 2 of which cancer patients) from the cities of Palermo and Agrigento." (PMID 32380732, 2020). "This suggests that the effect size of BARD1 c.1670G>C; p.Cys557Ser could be small, that is, it could confer a low–moderate risk to cancer relative to the high risk associated with BRCA1/BRCA2 pathogenic variants." (PMID 32726901, 2020). "Thus, the meiotic BRCA2 complex is central in meiotic HR, and its misregulation is implicated in cancer development." (PMID 32345962, 2020). "Thus, the role of BRCA1 upon estrogen challenges exceed the HR mechanism, which is also supported by different mutational processes revealed by distinct patterns of genomic imprints born by BRCA1 and BRCA2-mutated cancers." (PMID 33087072, 2020). "The main purpose of this review is to summarize the molecular biology associated with the representative cancer predisposition genes, BRCA1 and BRCA2, and to speculate on the missing link between normal and cancer cells." (PMID 32269964, 2020). "Because the frequency of BRCA1 and BRCA2 mutations in Indonesia are relatively low and the genetic tests were not widely available, our study did not specifically address the genetic risk for the development of bilateral cancer." (PMID 33204419, 2020). "Further studies are needed to determine whether the global genomic instability features of BRCA1/BRCA2-associated cancer are related to estrogen-induced DNA damage." (PMID 33299637, 2020). "The lncRNA, Malat1, controls the expression of genes involved in nuclear processes and synaptogenesis, while the expression of the lncRNA PCAT-1 causes a homologous recombination deficiency and the suppression of the tumor suppressor BRCA2, which has been linked to cancer." (PMID 32922377, 2020). "Additionally, BRCA1/BRCA2-mutated cancer carried microhomology-mediated deletions more frequently compared with the wild-type cancers." (PMID 32269964, 2020). "The germline mutation not only informs screening for secondary cancers and testing in relatives, BRCA2 mutations may also be associated with a worse prognosis and confer sensitivity to platinum-based chemotherapy and PARP-inhibitors." (PMID 32392735, 2020). "BRCA2 mutation increases the risks of aggressive PCa and other cancer types in Japanese males." (PMID 31631483, 2019). "Inherited mutations in the BRCA1 and BRCA2 (BRCA1/2) cancer susceptibility genes convey high lifetime risks of BC and OC, in the range of 40–66% and 13–46%, respectively, as well as, increased susceptibility for other malignancies, such as prostate and pancreatic cancers." (PMID 31771539, 2019). "PARG genetic knockdown sensitizes various cancer cells to chemotherapeutic agents and radiation and may cause tumor-specific killing in BRCA2-deficient cancer cells." (PMID 31827085, 2019). "Oxidative stress plays an important role in the development and progression of cancer, and therefore, the lower oxidative stress associated with the SNP may help to explain the lower cancer risk of BRCA2 carriers that harbor the SNP." (PMID 30747491, 2019). "Somatic mutations may also arise in HRR-associated genes; however, germline mutations are more common than somatic mutations in BRCA1- and BRCA2- mutated cancers." (PMID 30934991, 2019). "Olaparib is a PARP-inhibitor approved for clinical use in BRCA1- and BRCA2- deficient cancers." (PMID 31847370, 2019). "However, BRCA2-mutated cancers often become resistant to PARP inhibitors via different mechanisms, including recovery of BRCA2 functionality due to secondary BRCA2 mutations." (PMID 31284411, 2019).
cancer (continued). "Among the individuals with a pathogenic finding, 43.6% (126/289) of the alterations identified cases, the alteration identified occurred in the BRCA1 or BRCA2 genes, indicating the significant contribution of these two genes in hereditary cancer predisposition." (PMID 31159747, 2019). "Current strategies for female BRCA1 and BRCA2 mutation carriers to manage the elevated cancer risk include an intensified breast screening program (including magnetic resonance imaging, breast ultrasound, mammography, and breast palpation by a physician) as well as risk-reducing surgeries." (PMID 31370837, 2019). "In principle, the same approach could be applied to other in-frame exons, in which deletion would be expected to lead to an internally deleted protein such as exons 10, 11, 12, 17, 19, 26 and 27 of BRCA2 or in other cancer susceptibility genes." (PMID 29707112, 2018). "The unique divergence of the BRCA2 gene in Neanderthals compared to modern humans has been hypothesized to account for a differential susceptibility to cancer." (PMID 30564067, 2018). "A frequency of pathogenic variants in approximately 1:200 individuals for BRCA2 is therefore higher than might be expected from a population of individuals selected for non-cancer studies." (PMID 29641532, 2018). "Notably, cancer-associated truncating mutations that delete a C-terminal region of the BRCA2 protein retain RNAPII interaction but nevertheless diminish PAF1 recruitment to increase RNAPII accumulation and R-loop accrual at PPP sites." (PMID 29386125, 2018). "Hence, BRCA1/BRCA2 pathogenic mutations among other hereditary factors appeared to be a more prevalent cancer driver in this younger Asian BC cohort." (PMID 29713003, 2018). "Generation of inhibitors to proteins like SMARCAL1 and ZRANB3 could be beneficial for treating cancer with defects in HR since their knockdown reduced the level of chromosomal instability in BRCA2-deficient cells exposed to clastogenic agents." (PMID 31435521, 2018). "A third (7 patients) of the 20 BRCA2 mutated patients with cancer had multiple cancers." (PMID 29433453, 2018). "BRCA2 inactivation by cancer-associated mutations or RNAi-mediated depletion subverts this mechanism, impeding transcription elongation at the PPP sites of actively transcribed genes, accompanied by R-loop accumulation and DNA breakage mediated by the ERCC4 nuclease." (PMID 29386125, 2018). "Indeed, we show here that cancer-causing BRCA2 mutations are sufficient to trigger such defects in the patient-derived EUFA423 cell line." (PMID 29386125, 2018). "A significant number of patients (mostly BRCA2 mutation positive) developed multiple cancers, which may have important implications for cancer screening and prevention." (PMID 29433453, 2018). "BRCA1 and BRCA2 remain the main candidates for explaining the high risk of cancer in HBOC syndrome." (PMID 30453575, 2018). "BRCA2 mutations were also found to be associated with an increased risk of high-grade disease, progression to metastatic castrate resistant prostate cancer (mCRPC), and 5-year cancer-specific survival rates of 50% to 60%." (PMID 29690565, 2018). "Moreover, cancer risk varies by mutation location within the BRCA1 or BRCA2 genes and family history." (PMID 30518089, 2018). "Targeted sequencing of 30 MM cases with cancer familial aggregation identified a second BRCA2 variant of unknown significance: NM_000059.3(BRCA2):c.4534C>T (p.Arg1512Cys, rs80358684)." (PMID 30286154, 2018). "Regarding the number of SIMs in each protein, 79 sequences have a single motif, 15 sequences have two SIMs, 6 sequences have 3 SIMs, Tb927.9.7690 -one hypothetical protein- contains 4 SIMs and Breast Cancer Type 2 susceptibility protein (BRCA2, Tb927.1.640) harbors 14 SIMs." (PMID 29474435, 2018).
cancer (continued). "Of the 20 BRCA2 mutation carriers with cancer, over a third (7 patients) had multiple cancers." (PMID 29433453, 2018). "We analyzed mutations in the entire coding regions of the BRCA pathway genes, expression of breast cancer 2 (BRCA2), and mutations in hotspots of 50 cancer-associated genes in 42 surgically resected PDACs, and evaluated their associations with clinicopathological features." (PMID 29802286, 2018). "In addition, heterozygous carriers of a BRCA2 mutation in males show a significant increase in a variety of cancers." (PMID 31435521, 2018). "If the BRCA2 gene is mutated/changed the DNA could be corrupted developing genetic alterations that can lead to cancer." (PMID 29456628, 2018). "It was generally believed that when the repair of SSBs was blocked by PARP1 inhibition, SSBs would be converted into DSBs in S-phase that can only be repaired by HRR, therefore impaired HRR, as in cancer cells carrying BRCA1 or BRCA2 mutations, would render synthetic lethality with PARP1 inhibition." (PMID 29684820, 2018). "Of these 33 patients with cancer, the majority (20 patients) were found to carry a BRCA2 mutation." (PMID 29433453, 2018). "Importantly, these data also allow the further characterization of the ‘BRCAness’ phenotype by integrative network analysis of large datasets generated from BRCA2 mutation associated cancer cells with acquired resistance." (PMID 28617445, 2017). "Over the past decade, many association studies have been conducted to explore the role of the rs144848 N372H polymorphism in cancer risk, but it is still inconclusive whether this polymorphism in the BRCA2 gene is associated with susceptibility to cancer." (PMID 28418854, 2017). "We hypothesized MSI leads to mutations in DNA repair proteins including BRCA2 and cancer drivers including EGFR." (PMID 28591715, 2017). "Indeed, secondary mutations that rescue replication fork stability in BRCA2-deficient cancer cells, render them resistant to PARP inhibition." (PMID 28714471, 2017). "Therefore, tolerance of high levels of replication stress and endogenous DNA damage enable survival of BRCA2-deficient cancer cells." (PMID 28714477, 2017). "Epidemiological studies seem warranted to investigate the risk of cancer associated with BRCA2 mutations in such populations, particularly in light of the difficulty in testing these hypotheses in genetically engineered pre-clinical mouse models." (PMID 28575672, 2017). "In addition to finding an increased number of indels, we found a substantial increase in the number of spontaneously arising base substitutions that resembled a mutation signature associated with BRCA1 and BRCA2 mutant cancers." (PMID 27452521, 2017). "However, identification of a hereditary BRCA1/BRCA2 mutation in a family is often via initial diagnostic testing in an individual with cancer." (PMID 28780755, 2017). "In the present study, we aimed to accurately analyze the prevalence of mutations in BRCA1, BRCA2 and other cancer-predisposition genes in 272 Taiwanese patients with suspected HBOC based on both a cross-sectional hospital cohort and meta-analysis of published reports." (PMID 28961279, 2017). "DNA under replication could also potentially be exploited as an Achilles heel to treat BRCA2-deficient cancers by targeting components in the mitotic DNA synthesis pathway." (PMID 28904335, 2017). "We propose that targeting this pathway may represent a new strategy to modulate BRCA2-deficient cancer cell response to chemotherapeutics that cause fork degradation." (PMID 29038425, 2017). "Furthermore, cancer types such as melanoma and colon have been detected in families with BRCA2 mutations." (PMID 28947987, 2017). "Loss-of-function mutations in the BRCA1 and BRCA2 genes increase the risk of cancer." (PMID 27452521, 2017). "Our results suggest that an excessive production of NEIL2 enzyme, associated with the SNP, may have a deleterious effect modifying cancer risk susceptibility in BRCA2 mutation carriers." (PMID 29383107, 2017).
cancer (continued). "Although the etiology of OC is not yet fully understood, certain factors, including age, late childbearing, early onset at menarche, late menopause, and breast cancer 1 (BRCA1) and breast cancer 2 (BRCA2) mutations, are implicated in OC formation and development." (PMID 27835912, 2017). "Agents found to enhance 53BP1 nuclear body formation may further sensitize BRCA2-deficient cancer cells to therapy." (PMID 28904335, 2017). "These previously unrecognized cellular effects of aldehydes may potentiate genome instability and promote tissue-specific cancer evolution in patients who inherit pathogenic BRCA2 truncations, with implications for cancer biology and public health." (PMID 28575672, 2017). "Mutations truncating a single copy of the tumor suppressor, BRCA2, cause cancer susceptibility." (PMID 28575672, 2017). "Conversely, it is tempting to speculate that dietary supplementation with formaldehyde scavengers like Resveratrol may offer a future strategy to reduce cancer incidence in patients who carry pathogenic truncating mutations affecting BRCA2." (PMID 28575672, 2017). "Cancers associated with BRCA2 mutations can acquire chemo-resistance on relapse." (PMID 28617445, 2017). "Therefore, homologous recombination-deficient BRCA2 homozygous mutant cancer cells are an ideal target for PARP inhibitors." (PMID 29023372, 2017). "The variant of BRCA2 V2019I was found in patients with family history of cancer." (PMID 27701467, 2016). "Loss of heterozygosity in tumoral DNA confirms that the BRCA2 8765delAG mutation plays a role in adrenal oncogenesis supporting that ACC may be included in the spectrum of cancer-related BRCA2 gene." (PMID 27603373, 2016). "The observed ages at diagnosis of BC in TH, SH1, and SH2, and the distributions of tumor characteristics may also reveal the interactions of BRCA1 and BRCA2 mutations, which may have implications for modeling the cancer susceptibility in TH." (PMID 27836010, 2016). "Also BRCA2 germline mutations increase one’s risk to develop pancreatic, stomach, laryngeal, fallopian tube, or other cancers." (PMID 27630665, 2016). "Moreover, it has been suggested that the expression of PARP1, γH2AX, BRCA1, and BRCA2 are closely associated with the progression of various human malignant tumors." (PMID 27643881, 2016). "As PALB2 functions together with BRCA1 and BRCA2, in the same DNA-damage response pathway, it has been thought plausible that PALB2 mutations, similar to BRCA1 and BRCA2 mutations, could predispose to other cancer types." (PMID 27099641, 2016). "These molecular processes could explain the relation between this SNP and BRCA1 or BRCA2 mutations, on cancer risk." (PMID 27015555, 2016). "In addition, the underlying mechanisms of the observed hypersensitivity of BRCA2-deficient cancer cells towards apoptosis-inducing agents were explored." (PMID 26843614, 2016). "On the other hand, if testing for BRCA1 and BRCA2 focuses solely on unambiguously loss-of-function mutations with definitive effect on cancer risk, the cost per test may be markedly reduced." (PMID 26867194, 2016). "Clinical resequencing of a high‐risk cancer susceptibility gene such as BRCA1 (MIM #113705) or BRCA2 (MIM #600185) may reveal that a patient carries a clearly pathogenic sequence variant." (PMID 26913838, 2016). "BRCA2 mutations also predispose to cancers of the male breast, pancreas, prostate and other organs." (PMID 27881737, 2016). "Aiming at expanding the therapeutic exploitation of BRCA2-deficiency for cancer therapy, we investigated here whether deleterious BRCA2 mutations might confer increased susceptibility towards TRAIL-R-targeting agents." (PMID 26843614, 2016).